ASB6 (ankyrin repeat and SOCS box containing 6)
Description:
Probable substrate-recognition component of a SCF-like ECS (Elongin-Cullin-SOCS-box protein) E3 ubiquitin-protein ligase complex which mediates the ubiquitination and subsequent proteasomal degradation of target proteins. May play a role in the regulation of cell proliferation and autophagy by promoting the ubiquitination and degradation of SQSTM1.
Tractability: PROTAC: UniProt records ubiquitination sites on it; ubiquitination databases record sites on it; its protein half-life has been measured.
Gene: Protein-coding gene on chromosome 9 (129,634,602 to 129,642,169, reverse strand). Ensembl gene ENSG00000148331.
Subcellular location: Cytoplasm
Pathways (Reactome):
Immune System: Antigen processing: Ubiquitination & Proteasome degradation
Metabolism of proteins: Neddylation
Gene Ontology:
Molecular function: protein binding
Biological process: intracellular signal transduction; protein ubiquitination
Cellular component: cytosol; cytoplasm
Genetic constraint (gnomAD): Loss-of-function variants: 22 observed, 25.65 expected, observed/expected ratio (o/e) 0.86, 90% interval 0.61 to 1.23. The upper end of that interval is the gene's LOEUF score, 1.23, which puts it in group 5 of 6, group 1 being the genes least tolerant of losing a copy. Missense variants: 407 observed, 452.7 expected, observed/expected ratio (o/e) 0.9, 90% interval 0.83 to 0.98. Synonymous variants: 206 observed, 196.61 expected, observed/expected ratio (o/e) 1.05, 90% interval 0.93 to 1.18.
Homologues: Orthologues: chimpanzee ASB6 (100% identical), macaque ASB6 (99% identical), pig ASB6 (97% identical), dog ASB6 (96% identical), guinea pig ASB6 (92% identical), mouse Asb6 (89% identical), rat Asb6 (83% identical), tropical clawed frog asb6 (73% identical), zebrafish asb6 (52% identical).
Diseases named in the same sentence as ASB6 in open-access papers:
ASB6 is named in the same sentence as 14 diseases in open-access papers, as found by Europe PMC text mining. Sharing a sentence is not in itself a finding about the gene and the disease. The quoted sentences say what the papers report.
oral squamous cell carcinoma (5 papers, 2019 to 2024). "Another recent following study from the same group suggested that accumulation of ASB6 may impede ER stress and cause gain of stemness and metastasis feature of oral squamous cell carcinoma, although the underlying molecular mechanism remains elusive." (PMID 34164402, 2021). "ASB6 up-regulation by Areca nut extracts has been identified in normal keratinocytes and oral cancer cells, and is highly associated with a worse prognosis of oral squamous cell carcinoma." (PMID 31171715, 2019). "Later, ASB6 was found upregulated in oral squamous cell carcinoma, which is a possible consequence of exposure to Areca nut extracts and is co-related with poor survival." (PMID 34164402, 2021). "For example, hsa_circ_0001361 has been reported to accelerate the formation and metastasis of the vascular system in oral squamous cell carcinoma, while hsa_circ_0006156 inhibited colorectal cancer stemness and metastasis via RNF41-dependent ASB6 degradation." (PMID 38802851, 2024).
colorectal cancer (3 papers, 2022 to 2024). A primary or metastatic malignant neoplasm that affects the colon or rectum. "We showed that hypomethylation and copy number amplification of ASB6 in colorectal cancer are the causes of its abnormal overexpression." (PMID 38577591, 2024). "CNV analysis also showed that ASB6 copy number amplification was significantly associated with overexpression of ASB6 mRNA in colorectal cancer." (PMID 38577591, 2024). "Additionally, ASB6 copy number amplification was significantly associated with overexpression of ASB6 mRNA in colorectal cancer." (PMID 38577591, 2024). "However, the underlying role and mechanism of ASB6 in colorectal cancer, particularly its association with immune infiltration levels and its prognostic significance, remain to be fully elucidated." (PMID 38577591, 2024). "Furthermore, to explore the prognostic value of ASB6 in colorectal cancer, we constructed nomograms with independent risk factors that were significantly associated with OS and DSS in multivariate analysis." (PMID 38577591, 2024). "Additionally, the results from univariate Cox analysis suggested that both macrophages and ASB6 were identified as risk factors in colorectal cancer (both p-values < 0.05)." (PMID 38577591, 2024). "We found that, compared with adjacent normal tissues, the protein expression levels of ASB6 were significantly upregulated in colorectal cancer tissues, and patients with high protein levels of ASB6 had a poor prognosis." (PMID 38577591, 2024). "To explore the potential functions of ASB6 in colorectal cancer, we used Metascape to construct a protein-protein interaction (PPI) network for these ASB6-interacting proteins and performed GO and KEGG enrichment analysis." (PMID 38577591, 2024). "Most importantly, colorectal cancer patients with both high ASB6 expression and high M2 macrophage infiltration have worse overall survival." (PMID 38577591, 2024). "To further explore the potential mechanisms driving the upregulation of ASB6 in colorectal cancer, we analyzed its methylation levels through the GSCA database." (PMID 38577591, 2024). "The results revealed that colorectal cancer patients with high ASB6 expression were less sensitive to anti-PD-L1 immunotherapy, with a predictive AUC value of 0.669 (p = 0.032)." (PMID 38577591, 2024). "Taken together, this study demonstrates that ASB6 is an independent prognostic marker and potential therapeutic target in colorectal cancer." (PMID 38577591, 2024). "Methylation data analysis from TCGA revealed a significant downregulation of methylation levels of ASB6 in various cancers, including colorectal cancer." (PMID 38577591, 2024). "The expression level of ASB6 was significantly upregulated in colorectal cancer tissues with lymphatic invasion and distal metastasis." (PMID 38577591, 2024). "More importantly, colorectal cancer patients with abnormal ASB6 CNV (Amp) had worse OS, DSS and DFI." (PMID 38577591, 2024). "Considering the significant upregulation of ASB6 in colorectal cancer tissues, we identified 56 proteins that interact with ASB6 in colorectal cancer cells through immunoprecipitation-mass spectrometry analysis." (PMID 38577591, 2024). "Further analysis of TCGA clinical samples revealed that ASB6 mRNA expression levels were also significantly correlated with lymph node invasion, distal metastasis and other adverse events in colorectal cancer patients." (PMID 38577591, 2024). "In vitro cell experiments also indicated that ASB6 overexpression enhanced, while ASB6 knockout weakened, the migration ability of colorectal cancer cells." (PMID 38577591, 2024). "This work demonstrates that ASB6 is significantly overexpressed in various tumor tissues, including colorectal cancer." (PMID 38577591, 2024). "Collectively, these results demonstrate ASB6 expression correlates with colorectal cancer progression, further confirming its potential as a biomarker for poor prognosis in colorectal cancer patients." (PMID 38577591, 2024).
colorectal cancer (continued). "Further in vitro experiments also confirmed that ASB6 promotes the migration ability of colorectal cancer cells." (PMID 38577591, 2024). "In our study, we systematically analyzed the correlation between E3 ubiquitin ligase and deubiquitinating enzyme genes and the prognosis of colorectal cancer patients, and identified ASB6 as a key prognostic gene." (PMID 38577591, 2024). "To further clarify the role of ASB6 in the prognosis of colorectal cancer patients, we analyzed the protein expression levels of ASB6 in colorectal cancer tissue microarrays through immunohistochemistry analysis." (PMID 38577591, 2024). "Taken together, these results suggest that ASB6 may serve as an independent prognostic factor in colorectal cancer." (PMID 38577591, 2024). "Consequently, we analyzed the expression levels of ASB6 in pan-cancer and its copy number variations, immune infiltrations, clinical correlations, and prognostic values in colorectal cancer." (PMID 38577591, 2024). "In addition, the protein level of ASB6 was significantly upregulated in colorectal cancer tissues, and colorectal cancer patients with high ASB6 expression had worse prognosis." (PMID 38577591, 2024). "To further elucidate the correlation between ASB6 expression levels and clinicopathological characteristics, we stratified colorectal cancer patient tissues into low and high ASB6 expression groups based on the optimal cutoff value determined by overall survival analysis." (PMID 38577591, 2024). "In summary, we systematically analyzed the prognostic value of ASB6 in colorectal cancer." (PMID 38577591, 2024). "Moreover, pathological stage IV colorectal cancer tissues exhibited notably higher ASB6 expression than stage I and II patient tissues." (PMID 38577591, 2024). "In addition, colorectal cancer patients with high ASB6 expression were insensitive to anti-PD-L1 immunotherapy." (PMID 38577591, 2024). "Survival analysis also showed that ASB6 is significantly associated with overall survival (OS), progression-free interval (PFI), disease-specific survival (DSS) and disease-free interval (DFI) in various cancers, including colorectal cancer." (PMID 38577591, 2024). "Subsequent survival analysis of ASB6 copy number alteration (CNA) subgroups (Amp, Dele and WT) in colorectal cancer patients revealed that patients with ASB6 copy number amplification (Amp) had worse OS, DSS and DFI compared to those with wild-type (WT) and deletion (Dele) ASB6." (PMID 38577591, 2024). "Moreover, the combined survival analysis of ASB6 expression and M2 Macrophage levels also revealed that patients with high ASB6 expression and high M2 Macrophage levels exhibited shorter overall survival in colorectal cancer (p = 0.083)." (PMID 38577591, 2024). "In sum, these results collectively indicate that ASB6 could serve as a novel prognostic marker and potential therapeutic target in colorectal cancer." (PMID 38577591, 2024). "Therefore, we hypothesize that ASB6 facilitates M2 macrophage polarization, thereby promoting colorectal cancer progression." (PMID 38577591, 2024). "To investigate whether ASB6 facilitates colorectal cancer progression, we first established stable DLD-1 colorectal cancer cell lines with overexpression or knockout of ASB6, then performed Western blot analysis to confirm the stable overexpression and knockout of ASB6 in these cell lines." (PMID 38577591, 2024). "Univariate and multivariate analyses also showed that ASB6 can serve as an independent prognostic factor for OS and DSS in colorectal cancer." (PMID 38577591, 2024). "In colorectal cancer tissues with lymph node or vascular invasion, ASB6 expression was markedly higher relative to non-invaded tissues." (PMID 38577591, 2024). "Notably, we identified ASB6 (Ankyrin repeat and SOCS box protein 6) as a key prognostic gene in colorectal cancer." (PMID 38577591, 2024).
oral cancer (3 papers, 2012 to 2022). "The up-regulation of ASB6 is associated with the elevation of intracellular ROS in oral cancer cells." (PMID 35818360, 2022). "A recent study also showed that overexpression of ASB6 can decrease intracellular ROS and endoplasmic reticulum stress in the deprived media-induced stress of oral cancer cells." (PMID 35818360, 2022).
colon adenocarcinoma (1 paper, 2024). "Furthermore, high ASB6 expression correlated with shorter DSS, OS, and PFI in colon adenocarcinoma (COAD) and lower grade glioma (LGG) as well." (PMID 38577591, 2024).
colorectal adenocarcinoma (1 paper, 2022). The most common type of colorectal carcinoma. "UALCAN data analysis revealed that ASB6 was remarkably upregulated in colorectal adenocarcinoma (COAD), and COAD patients with high ASB6 expression exhibited unfavorable OS." (PMID 36446779, 2022).
hepatocellular carcinoma (1 paper, 2021). A malignant tumor that arises from hepatocytes. "Functionally, ASB6 overexpression can inhibit the proliferation of MEF and hepatocellular carcinoma cells by reducing p62 protein level, and impair the occurrence of autophagy." (PMID 34164402, 2021).
liver cancer (1 paper, 2021). An epithelial or non-epithelial malignant neoplasm that arises from the liver. "Since p62 has been reported to play an important role in the occurrence and development of liver cancer, we next investigated whether ASB6 has a function in liver cancer cells by regulating p62." (PMID 34164402, 2021). "In order to test whether ASB6 is indeed an endogenous interacting protein of p62, we next performed Co-IP experiment with lysate generated from human liver cancer cell line Huh1, in which the tumor-promoting effect of p62 has been validated." (PMID 34164402, 2021).
cancer (5 papers, 2022 to 2025). A tumor composed of atypical neoplastic, often pleomorphic cells that invade other tissues. "The results of the univariate and multivariate Cox analyses showed that cancer status and ASB6 expression level were significantly associated with overall survival (OS)." (PMID 38577591, 2024). "Meanwhile, cancer status, tumor stage, and ASB6 expression level were significantly correlated with disease-specific survival (DSS)." (PMID 38577591, 2024). "We found an increased abundance of the transcription factors AHDC1 and ERF, as well as proteins associated with cancer stemness (AQP5 and ASB6), which were higher expressed in SBT-MP when compared to SBT." (PMID 38014221, 2023). "ASB6 acts as an adapter protein which participates in the activation of insulin signaling, however, little is known about its role in cancer." (PMID 36446779, 2022). "In addition, we analyzed the mRNA expression levels of ASB6 in pan-cancer and found that ASB6 is significantly upregulated in many tumors." (PMID 38577591, 2024). "Additionally, high ASB6 expression weakly correlated with M stage (M1 vs. M0) and cancer status (With tumor vs. Tumor-free)." (PMID 38577591, 2024). "However, there is currently limited research on the mechanisms and roles of ASB6 in cancer." (PMID 38577591, 2024). "The cancer-promoting proteins (NCBP2, AMD, MER34, ENC1, and COA4) were suppressed, while the secretory glycoprotein (A1BG) and ROS-reducing protein (ASB6) were overexpressed in the treatment group." (PMID 35818360, 2022). "The volcano plot revealed that the cancer-promoting proteins (NCBP2, AMD, MER34, ENC1, and COA4) were down-regulated, while the secretory glycoprotein (A1BG) and ROS-reducing protein (ASB6) were up-regulated in the treatment group." (PMID 35818360, 2022).
tumor (4 papers, 2021 to 2024). "ASB6 has been reported to play significant roles in several biological processes, including tumor stemness and endoplasmic reticulum stress." (PMID 38577591, 2024). "In vivo experiments showed that overexpression of circFNDC3B or RNF41 alone suppressed tumor growth, stemness, and liver metastasis through modulation of ASB6." (PMID 36831219, 2023). "Collectively, these data indicate that circFNDC3B or RNF41 overexpression suppresses tumor growth, stemness and liver metastasis via modulating ASB6 in vivo." (PMID 36446779, 2022). "IHC analysis further confirmed the circFNDC3B- or RNF41-mediated downregulation of ASB6 in tumor tissues, and the proliferation marker Ki-67 and stemness marker CD133 were also reduced by circFNDC3B or RNF41 overexpression in vivo." (PMID 36446779, 2022). "In vivo experiments further showed that circFNDC3B or RNF41 overexpression repressed tumor growth, stemness and liver metastasis via modulating ASB6." (PMID 36446779, 2022). "m6A-modified circFNDC3B plays a tumor suppressive role in colon cancer CSCs by increasing RNF41 mRNA stability and expression and thus promoting ASB6 degradation via RNF41-mediated ubiquitination." (PMID 36831219, 2023). "Collectively, we hypothesize that ASB6-mediated ubiquitination and degradation of ATP5F1A suppresses oxidative phosphorylation and enhance glycolysis to facilitate tumor progression." (PMID 38577591, 2024).
ASB6 also shares sentences with these, for which no sentence is quoted: glioma (1 paper); infection (1); lung squamous cell carcinoma (1); prostate adenocarcinoma (1); rectum adenocarcinoma (1).